MTOR (mechanistic target of rapamycin kinase)
Diseases named in the same sentence as MTOR in open-access papers (continued):
Sharing a sentence is not in itself a finding about the gene and the disease.
ovarian carcinoma (continued). "For this purpose, we determined the activation of pro‐survival AKT/mTOR pathway already reported to be engaged in ovarian cancer progression." (PMID 39431349, 2024). "TCP1 encodes a molecular chaperone protein that modulates the PI3K/AKT/mTOR signaling pathway, thereby promoting ovarian cancer cell proliferation and enhancing drug resistance in acute myeloid leukemia." (PMID 38300336, 2024). "What's more, mutant activation of AKT was generated in a context of HDAC7 inhibition to fully demonstrate that HDAC7 promotes the malignant progression of ovarian cancer through the AKT/mTOR pathway." (PMID 39431349, 2024). "In high grade ovarian cancer, high expression of GGCT has been confirmed to correlate with poorer OS, and GGCT facilitates the progression of ovarian cancer by activating the PI3K/AKT/mTOR pathway." (PMID 38914714, 2024). "One study demonstrated that PD-L1 acts as an upstream regulator of mTOR, activating the Akt–mTOR axis and promoting the proliferation of human ovarian cancer cells." (PMID 38892329, 2024). "Studies have shown that NC can induce the apoptosis of ovarian cancer cells through the Akt/mTOR pathway, which is inconsistent with the results of this study." (PMID 39457946, 2024). "In summary, Har not only promotes autophagy by regulating the PI3K/AKT/mTOR/FOXO3 signalling pathway to play an anti-ovarian cancer role, but also promotes ferroptosis and pyroptosis in ovarian cancer." (PMID 38499622, 2024). "Aberrant activation of oncogenic pathways, such as PI3K/mTOR, in ovarian cancer cells is key to tumor drug resistance." (PMID 38238825, 2024). "OGN overexpression also changed epithelial-mesenchymal transition (EMT) markers and promoted mTOR and Akt phosphorylation in ovarian cancer cells." (PMID 38402185, 2024). "The oncogenic role of PI3K-Akt-mTOR signaling in ovarian cancer is to promote uncontrolled cell proliferation, anti-apoptosis, and tumorigenesis." (PMID 38466483, 2024). "Under the acidic conditions of the tumor microenvironment, biotin helical nanoparticles can rapidly cleave and release miR497 and TP, as well as synergistically induce ovarian cancer cell apoptosis by inhibiting the PI3K/AKT/mTOR signaling pathway." (PMID 38832992, 2024). "In our study, we examined the PTEN protein, a primary negative regulator of the PI3K/Akt/mTOR signaling pathway, in relation to the impact of MB-591 on ovarian carcinoma cells." (PMID 38675591, 2024). "In conclusion, a miRNA/mRNA axis in ovarian cancer CAFs modulating the proliferative and invasive abilities of ovarian cancer cells was demonstrated, possibly through the Akt/mTOR pathway." (PMID 38402185, 2024). "Deregulation of PI3K/PTEN/Akt/mTOR signaling was observed in solid tumors and in pancreatic and ovarian cancer and plays a crucial role in drug resistance, indicating mTOR as an attractive drug target." (PMID 38675189, 2024). "In conclusion, Har exerts its anti-ovarian cancer effect not only by promoting autophagy by regulating the PI3K/AKT/mTOR/FOXO3 signalling pathway but also by promoting ferroptosis and pyroptosis." (PMID 38499622, 2024). "Overall, above data demonstrate that HDAC7 fuels ovarian cancer progression by regulating the AKT/mTOR pathway." (PMID 39431349, 2024). "Blocking PI3K/Akt/mTOR signaling pathway attenuates ovarian cancer chemoresistance to DDP through reversing EMT." (PMID 37304662, 2023). "This study demonstrated that NC can inhibit the expression and phosphorylation of Akt and mTOR proteins through WB experiments, indicating that NC can affect autophagy and promote apoptosis of ovarian cancer cells through Akt/mTOR pathway." (PMID 37317923, 2023). "Subsequently, the authors identified a new SIRT1 inhibitor, MHY2245, which induces autophagy and inhibits energy metabolism in human ovarian cancer cells through the PKM2/mTOR pathway, providing new insights into the treatment of ovarian cancer." (PMID 36975503, 2023).
ovarian carcinoma (continued). "The research verified that overexpression of GAS5 inhibited the PI3K/AKT/mTOR signaling pathway in ovarian cancer cells." (PMID 37639158, 2023). "Previously, other researchers have also reported that the combination of microtubule-targeting agents (e.g., paclitaxel and eribulin) and various PI3K/AKT/mTOR inhibitors suppressed the EMT pathway in ovarian cancer." (PMID 37835582, 2023). "Ovarian cancer is characterized by multiple changes in the proteins involved in the PI3K/AKT/MTOR signaling pathway through activation (in 65–75% of cases); thus, it is responsible for the increased invasion capacity of ovarian cancer." (PMID 37958970, 2023). "PI3K/AKT/mTOR signaling pathway plays an important role in cell proliferation and apoptosis of ovarian cancer cells." (PMID 36670423, 2023). "Their inherent binding affinities and preliminary insights into protein interactions imply a potential for tailoring these phytochemicals into specific degraders targeting the PI3K/Akt/mTOR pathway in ovarian cancer." (PMID 38239204, 2023). "This suggests that TZ can modulate endothelial cell function and inhibit angiogenesis through the VEGFR-2/PI3K/mTOR pathway, making it a potential anti-angiogenic agent in ovarian cancer (OC) treatment." (PMID 38074670, 2023). "The mediating role of MFN2 in mitophagy reduces ROS levels and suppresses ovarian cancer progression through the AMPK/mTOR/ERK signaling pathway." (PMID 38038814, 2023). "In the present study, we attempted to explore the correlation between the mechanism of cardamonin-induced oxidative stress and ERK1/2 and mTOR pathways in ovarian cancer cells." (PMID 37304865, 2023). "Despite this evidence, the function of mTOR in the transformation process of endometriosis into ovarian cancer remains poorly understood." (PMID 37627318, 2023). "Previous research found that MCP-1 can facilitate tumor cell migration and omental metastasis of ovarian cancers via the PI3K/AKT/mTOR pathway and downstream HIF-1α and VEGF-A." (PMID 37298699, 2023). "A recent study indicated the antimetastatic effect of metformin on ovarian cancer by inhibiting mTOR-mediated HIF-1α activation." (PMID 37760498, 2023). "REST regulates the growth and survival of ovarian cancer cells by regulating mTOR signaling pathways." (PMID 37600577, 2023). "The results suggest that we can use inhibitors of the PI3K/AKT/mTOR pathway to inhibit ovarian cancer development." (PMID 37639158, 2023). "This concerted approach - the synergistic inhibition of mangiferin and curcumin as enhanced nano-drugs - has the potential to redefine therapeutic strategies for PI3K/Akt/mTOR pathway-mediated ovarian cancer." (PMID 38239204, 2023). "Glutamine metabolism is one of the hallmarks of ovarian cancer and is known to stimulate the mTOR/MAPK and STAT3 signaling pathways, and inhibition of glutamine metabolism has been shown to provide therapeutic benefits." (PMID 37375634, 2023). "All these results suggest that NC can effectively promote autophagic apoptosis of ovarian cancer cells through Akt/mTOR signaling pathway, which provides a theoretical basis for further research on NC's inhibition of tumor cell growth." (PMID 37317923, 2023). "Flow cytometry was used to detect the effect of NC on apoptosis and autophagy of ovarian cancer cells, and the Akt/mTOR signaling pathway in ovarian cancer was evaluated by using western blot experiment." (PMID 37317923, 2023). "In contrast, daphnetin triggered ROS-induced cell death and induced cytoprotective autophagy by modulating the AMPK/Akt/mTOR pathway in ovarian cancer." (PMID 36593951, 2023). "PRKAR1B-AS2 promotes tumour growth and confers chemoresistance by modulating the PI3K/AKT/mTOR pathway in ovarian cancer." (PMID 36056355, 2022). "RAD21 promoted malignant biological behaviors of ovarian cancer cells by activating the Akt/mTOR signaling pathway and reduced the sensitivity of cancer cells to PARP inhibitors by affecting the DSB repair." (PMID 35860572, 2022).
ovarian carcinoma (continued). "A recombinant fragment of human SP-D (rfhSP-D) decreases the motility and proliferation of ovarian cancer cells by inhibiting the mammalian target of rapamycin (mTOR) activity, increasing caspase 3 cleavage, and inducing pro-apoptotic genes Fas and TNF-α." (PMID 36077500, 2022). "Our risk model, composed of six proteins (GSK3α/β, HSP70, MEK1, MTOR, BAD, and NDRG1), can predict survival of ovarian cancer patients effectively, thereby helping prognosis monitoring and decision making." (PMID 35840928, 2022). "Previous studies have found that poricoic acid A, the main component of Poria cocos, can induce apoptosis in ovarian cancer cells by regulating the mTOR/p70s6k signaling axis." (PMID 35401186, 2022). "Treatment with the inhibitor cocktail decreased ovarian cancer metastasis and aggressiveness by inhibiting the mTOR and TAK1 signaling pathways." (PMID 35216285, 2022). "Ovarian cancer cells showed attenuation in expression of p38 kinase, Akt and mTOR following treatment with melatonin." (PMID 36581900, 2022). "In ovarian cancer patients the PI3K/AKT/mTOR and RAS/RAF/MEK/ERK kinase signaling pathways are frequently dysregulated, making them potential targets of therapeutic inhibitors." (PMID 35053555, 2022). "Approximately 70% of ovarian cancer patients present with overexpressed PI3K/AKT/mTOR cascade; thus, using inhibitors to target this pathway is an important strategy to treat ovarian cancer." (PMID 35299895, 2022). "AZD2014 is another second-generation mTOR inhibitor that attenuates myeloid-derived suppressor cell recruitment and blocks cell proliferation in ovarian cancer." (PMID 36539659, 2022). "ATG16L1 has been reported to promote tumorigenesis in ovarian cancer by activating the PI3K/AKT/mTOR pathway." (PMID 35524319, 2022). "Studies demonstrated that PI3K/AKT/mTOR pathway, one of the most important signaling pathways for therapeutic intervention in ovarian cancer, has been reported as the frequently altered signaling pathway in ovarian cancer." (PMID 35439731, 2022). "Consistently, the expression of p70S6K, an important downstream of p-mTOR, was down-regulated by dezocine in ovarian cancer cells." (PMID 36568517, 2022). "The PI3K/Akt/mTOR axis is essential in abnormally proliferated ovarian cancer cells, and using pathway inhibitors to reduce pathway activity is expected to improve therapeutic effects in patients with ovarian cancer." (PMID 36052284, 2022). "The PI3K/Akt/mTOR signaling pathway was found to be potentially affected by m6A regulators in most cancers such as gastrointestinal cancer and ovarian cancer, which was consistent with our results." (PMID 35615374, 2022). "Many PI3K/Akt/mTOR pathway inhibitors for ovarian cancer have been reported in preclinical and clinical data." (PMID 36483919, 2022). "It is worth noting that the PI3K/AKT/mTOR signaling pathway is activated in about 70% of ovarian cancers, which suggested that one or more correlated pathways are affected." (PMID 35281608, 2022). "The latest studies have shown that PI3K/AKT/mTOR can also be activated by METTL3-mediated M6A modification in ovarian cancer and retinoblastoma." (PMID 35574388, 2022). "The purpose of this study was to investigate the effect of BJOE on the regulation of mammalian rapamycin target protein (mTOR) autophagy signal pathway and related autophagy factors on ovarian cancer cells through miR-8485." (PMID 35959437, 2022). "Several drug inhibitors aimed at targeting different components of the PI3K/AKT/mTOR pathway are currently being assessed in phase I and II clinical trials in ovarian cancer with modest results." (PMID 35292711, 2022). "This interaction activates the phosphoinositide-3-kinase (PI3K)-mTOR pathway, which promotes the proliferation and survival of ovarian cancer cells." (PMID 35216285, 2022).
ovarian carcinoma (continued). "PD triggered apoptosis in cancer cells, namely ovarian cancer cells, and protected against inflammatory damage through the phosphoinositide, 3-kinase/protein kinase B/mammalian target of rapamycin (mTOR) pathway." (PMID 36364001, 2022). "ECH can also inhibit the proliferation and migration of ovarian cancer cells via PI3K/Akt/mTOR pathway." (PMID 35814196, 2022). "In conclusion, our research showed that STS synergistically enhanced the toxicity of niraparib on ovarian cancer cells through the Akt/mTOR signalling pathway." (PMID 35016681, 2022). "Given the important role of the PI3K/Akt/mTOR signaling pathway in cancer, it has been reported that CMG002, a PI3K/mTOR dual-target inhibitor, overcomes chemoresistance in ovarian cancer." (PMID 35646704, 2022). "Since cytoplasmic TR beta was discovered to stimulate PI3K and mTOR signaling, two pathways highly relevant for tumor cell growth and survival, this ‘non-genomic’ activity of cytoplasmic TR beta might also explain why (cytoplasmic) TR beta was linked to ovarian cancer aggressiveness in our analysis." (PMID 35269838, 2022). "Previous studies have reported that blockade of the PI3K/Akt/mTOR signaling pathway alleviates ovarian cancer chemoresistance through reversing the EMT process." (PMID 35646704, 2022). "The metabolic changes observed in ovarian cancer are facilitated by signaling pathways PI3K/AKT/mTOR and JAK/STAT." (PMID 36230617, 2022). "We did not only confirm the importance of DNA repair and transcriptional regulation directly in HGSC tissues, but also identified RNA splicing and the PI3K/AKT/mTOR pathway as playing an important role in ovarian cancer." (PMID 35292711, 2022). "The PI3K/AKT/mTOR signaling pathway is thought to be aberrant in approximately 70% of ovarian cancers." (PMID 35053555, 2022). "It has been demonstrated that neferine can inhibit angiogenesis in ovarian cancer by inhibiting the mTOR/p70S6K signaling pathway while inducing autophagy and inhibiting M2 macrophage polarization." (PMID 35684449, 2022). "There have been, and continue to be, many clinical trials using PI3K/mTOR inhibitors, including those for epithelial ovarian cancers." (PMID 35321751, 2022). "Mitogen-activated protein kinase/extracellular signal-regulated kinases (MAPKs/ERK) and PI3K/AKT/mTOR pathways are critical in controlling the growth and survival of ovarian cancer cells." (PMID 36523985, 2022). "Melatonin is claimed to be involved in the autophagy and apoptosis of several types of cancer cells such as hepatocellular carcinoma, melanoma and ovarian carcinoma via PI3K/Akt/mTOR pathway and ER stress response." (PMID 36581900, 2022). "As previously reported, IGF1 acts as an inducer for human ovarian cancer by activating the PI3K/AKT/mTOR signaling, which is in line with our finding." (PMID 35964060, 2022). "For instance, the dual PI3K/mTOR inhibitor PKI-402 inhibits the growth of ovarian cancer cells via degradation of Mcl-1." (PMID 35783514, 2022). "The research of Che and coworkers suggested that autophagic cell death is induced by grifolin in human ovarian cancer cells by inhibiting the Akt/mTOR/S6K pathway." (PMID 35566312, 2022). "In this study, we found that CRABP2 was markedly inhibited by dezocine in ovarian cancer cells at both mRNA and protein levels by inhibiting the Akt/mTOR signaling pathway activation." (PMID 36568517, 2022). "It was announced that cardamonin had an anti-inflammatory effect by suppressing mTOR in ovarian cancer." (PMID 35317111, 2021). "It has been demonstrated that autophagy is impaired by the activation of the Akt/mTOR pathway in ovarian cancer cells." (PMID 34131394, 2021). "Neferine can induce autophagy in various cancer cells, such as human ovarian cancer via the inactivation of mTOR and the activation of p38 MAPK/JNK signaling pathways." (PMID 34575981, 2021).
ovarian carcinoma (continued). "Triptolide also indirectly inhibits NF-ĸB signaling through the AKT/GSK3β/mTOR pathway and induces apoptosis in ovarian cancer by inhibition of NF-ĸB expression." (PMID 34213719, 2021). "Frequent activation of the PI3K/AKT/mTOR pathway in many cancers, including ovarian cancer, suggests the PI3K/AKT/mTOR pathway to be an attractive target for therapeutic intervention." (PMID 35582310, 2021). "Taken together, our research is the first to identify that focal adhesion kinase inhibitor BI853520 inhibits cell proliferation, migration and EMT process through PI3K/AKT/mTOR signaling pathway in ovarian cancer." (PMID 35201437, 2021). "The treatment with oridonin at 2.5 to 10 μM for 24 h decreased cell migration and invasion of SKOV3 ovarian cancer cells by blocking the phosphorylation of the mTOR signaling pathway." (PMID 33546106, 2021). "We will present pre-clinical evidence and clinical trial outcomes for inhibitors targeting different nodes of the PI3K/AKT/mTOR pathway, and highlight past and upcoming clinical trials for ovarian cancers." (PMID 35582310, 2021). "Here, we studied the functions of RBM11 in ovarian cancer and found that RBM11 was overexpressed in ovarian cancer tissues and exerts oncogenic roles in ovarian cancer through activating Akt/mTOR signaling." (PMID 34434291, 2021). "Molecular targets and pathways currently under investigation for drug development in ovarian cancers include, cell cycle inhibitors, mTOR inhibitors, and PI3K inhibitors." (PMID 34224310, 2021). "FOXM1 transcriptional targets linked to platinum resistance in ovarian cancer include exonuclease 1 (EXO1), a DNA repair protein recruited to double-stranded breaks, and PCLAF, a protein that activates the PI3K/AKT/mTOR signaling pathway." (PMID 34205406, 2021). "For example, the low expression of CADM1 in OV has been reported to inhibit the proliferation and migration of ovarian cancer cells through the PI3K/Akt/mTOR pathway." (PMID 33763357, 2021). "The anti-invasive and anti-metastatic effects of oridonin via inhibiting the mTOR pathways have been studied in ovarian cancer." (PMID 33546106, 2021). "RBM11 is elevated in ovarian cancer tissues and promotes ovarian cancer growth and invasion through activating the Akt/mTOR signaling pathway." (PMID 34434291, 2021). "It is clear that the mTOR signaling pathway has an important role in malignancy, as it is frequently hyperactivated in a wide range of tumors, including ovarian cancer." (PMID 35582305, 2021). "Limited numbers of dual PI3K/mTOR inhibitors have progressed to clinical trials in ovarian cancer, despite numerous pre-clinical studies showing positive anti-tumor activity and outcomes." (PMID 35582310, 2021). "Based on these results, resistin appears to promote the proliferation of ovarian cancer cells through the mTOR signaling pathway." (PMID 34659568, 2021). "BLP also suppressed ROS generation and regulated Akt/mTOR signaling transduction in human ovarian cancer." (PMID 34641493, 2021). "Had an inhibitory effect on the growth and migration of ovarian cancer cells by inhibiting the activation of mTOR and the induction of HIF1α." (PMID 35011278, 2021). "Mechanically, we found that RBM11 positively regulated Akt/mTOR signaling pathway activation in ovarian cancer cells." (PMID 34434291, 2021). "On the basis of the promising activity of these compounds on other cancer types, mTOR inhibitors have been tested on ovarian cancer." (PMID 35582305, 2021). "Potential small molecular drugs (PI3K and mTOR inhibitors) were found for treatment of ovarian cancer." (PMID 33748162, 2021). "In DIRAS3-mediated dormancy of ovarian cancer cells, mTOR inhibition by DIRAS3-induced translocation of FOXO3 and TFEB to the nucleus, which stimulated the transcription of multiple autophagy-related genes." (PMID 34832087, 2021).